RAMACL (RNA guanine-7 methyltransferase activating subunit like)
Description:
Component of the mRNA-capping methyltransferase RNMT:RAMAC complex that methylates the N7 position of the added guanosine to the 5'-cap structure of mRNAs.
Synonyms: dJ427A4.2; C6orf119; FAM103A2P; RAMMETL; RAMMETP1
Gene: Protein-coding gene on chromosome 6 (166,583,009 to 166,586,678, reverse strand). Ensembl gene ENSG00000235272.
Subcellular location: Nucleus
Subcellular location (Human Protein Atlas): Nucleoplasm
Gene Ontology:
Molecular function: enzyme activator activity; RNA binding
Biological process: 7-methylguanosine mRNA capping; RNA 5'-cap (guanine-N7)-methylation
Cellular component: mRNA capping enzyme complex; nucleus
Genetic constraint (gnomAD): Loss-of-function variants: 9 observed, 10.91 expected, observed/expected ratio (o/e) 0.82, 90% interval 0.5 to 1.43. The upper end of that interval is the gene's LOEUF score, 1.43, which puts it in group 5 of 6, group 1 being the genes least tolerant of losing a copy. Missense variants: 103 observed, 111.37 expected, observed/expected ratio (o/e) 0.92, 90% interval 0.79 to 1.09. Synonymous variants: 29 observed, 38.35 expected, observed/expected ratio (o/e) 0.76, 90% interval 0.56 to 1.03.
Homologues: Orthologues: chimpanzee RAMAC (100% identical), macaque RAMAC (100% identical), dog RAMAC (94% identical), guinea pig Ramac (90% identical), mouse Ramac (88% identical), rat Ramac (85% identical), mouse Ramacl (73% identical). Paralogues in human: RAMAC (99% identical).